MTOR (mechanistic target of rapamycin kinase)
Diseases named in the same sentence as MTOR in open-access papers (continued):
Sharing a sentence is not in itself a finding about the gene and the disease.
cancer (continued). "Similarly, GSEA of low‐FREM1 expression group based on Hallmarks data set confirmed eight activated pathways involving cell metabolism (glycolysis, oxidative phosphorylation), cell‐cycle regulation (DNA repair, G2M checkpoint), and cancer‐related signaling (Myc‐targets, mTOR signaling, E2F targets)." (PMID 33058542, 2020). "Therefore, understanding the mechanisms by which cells become resistant to rapalogs may guide the development of successful mTOR-targeted cancer therapy." (PMID 33144562, 2020). "The Akt/mTOR pathway may affect gene expression and enzyme activity, increase glycolysis and lactate accumulation in the cells, and to prompt aerobic glycolysis (Warburg effect) in either cancer cells or normal cells." (PMID 32318579, 2020). "However, if cancer cells have already reached some degree of resistance, the inhibition of mTOR can also generate JNK activation, P-ERK upregulation, and Bcl-2/Bcl-xL phosphorylation in the breast, gastric and esophageal cancer, with subsequent activation of protective autophagy." (PMID 33194736, 2020). "Here, targeting the mTOR pathway may prevent cancer metastasis driven by CXCL12/CXCR4 interaction." (PMID 32483450, 2020). "Besides PI3K-Akt and mTOR regulation, miRNAs influence Transforming Growth Factor-β1 (TGF-β1) signaling at multiple levels and the dysregulation of TGF-β1 signaling is often linked to several diseases, including cancer." (PMID 33364499, 2020). "Also, mTOR regulates the invasion and motility of cancer cells." (PMID 36046386, 2020). "Whether PI3K/AKT/mTOR pathway or Wnt/β-catenin pathway is dysregulated in human cancer development?" (PMID 32501811, 2020). "In addition, the alternated cancer‐related hallmark pathway was also found, such as KRAS signaling up, epithelial–mesenchymal transition and phosphatidylinositol‐3‐kinase (PI3K)/Akt and the mammalian target of rapamycin (mTOR) signaling." (PMID 32686362, 2020). "To gain a better understanding the regulatory mechanism of SLC39A7 in GC, we assessed whether SLC39A7 down-regulation influences the Akt/mTOR signaling pathway which is often aberrantly boosted in various human cancers and affects cell proliferation and apoptosis." (PMID 32109290, 2020). "Hence, it could be speculated that inhibition of mTOR signaling by PP242 acts by blocking β-FAO in cancer cells by reducing carnitine levels." (PMID 33067464, 2020). "With regards of the reduced activity of mTOR that may lead to impaired suppression of autophagy, several studies have demonstrated that intermediates of the autophagic-lysosomal proteolytic system are also increased in patients with different types of cancer." (PMID 32230855, 2020). "Thus, enormous efforts have been made to develop mTOR inhibitors for targeted cancer therapy." (PMID 32541839, 2020). "mTOR activation played an important role in tumor cell growth, protein synthesis, cell metabolism, and other physiological and pathological processes, and its over activation could lead to the proliferation of a variety of cancer cells." (PMID 32595698, 2020). "In addition, the mammalian target of rapamycin (mTOR) seems to play a significant role in the metabolic reprogramming of tumor cells, specifically mTOR complex 1 (mTORC1), which is activated in the majority of cancers." (PMID 32183017, 2020). "Here, we provide the first evidence for an involvement of the mTOR/PI3K pathway in RTK trafficking and expression, thus enforcing the proof of concept that mTOR complexes may be further considered as potential tools for pharmacological interventions in cancer, including GBM." (PMID 32823532, 2020). "The introduction of the serine/threonine protein kinase mechanistic target of rapamycin (mTOR) inhibitors in transplantation pursued the challenge of reducing nephrotoxicity related to the use of CNI, so as to increase the life of the graft and to decrease the risk of cancer or infections." (PMID 32290462, 2020).
cancer (continued). "However, some anti-cancer drugs can activate the Akt/mTOR signaling pathways." (PMID 33336024, 2020). "Also involved is the PI3K/AKT/mTOR pathway, which is frequently activated in human cancer." (PMID 33127874, 2020). "For instance, dysregulation of Wnt canonical and PI3K/AKT/mTOR signaling pathways, caused by an altered methylation status in a variety of genes, has been associated with resistance to current treatments (taxanes, DTX, cisplatin, TKI, etc.)in many types of cancer." (PMID 32850327, 2020). "Therefore, the association between mTOR rs2295080 and overall cancer susceptibility has not been comprehensively evaluated." (PMID 32597485, 2020). "Moreover, AMPK is shown to inhibit PI3K/AKT/mTOR signaling, which is activated in many cancers." (PMID 32807122, 2020). "Thus, in our study, we introduced a mTOR inhibitor and show that addition of pan FGFR inhibitor AZD4547 alone and in combination with mTOR inhibitor rapamycin inhibited cell growth associated with E2/E4/E5 in HPV positive cancers." (PMID 32848210, 2020). "GSEA enrichment analysis showed that the STK11 mutations were associated with multiple cancer-related pathways, including oxidative phosphorylation, unfolded protein response, peroxisome, protein secretion, Wnt/beta catenin signaling and PI3K/AKT/mTOR signaling." (PMID 33425731, 2020). "Similarly to α-humulene, a suppression in the PI3K/Akt/mTOR/S6K1 signaling by β-caryophyllene oxide, associated to a ROS-mediated activation of mitogen-activated protein kinases (MAPKs) in breast MCF7 and prostate PC3 cancer cells, was reported." (PMID 33081075, 2020). "Upregulated PI3K/AKT/mTOR signaling, the occurrence of mutational changes in the PI3K pathway and emerging clinical data from trials with PI3K inhibitors make PI3K an attractive target for cancer therapy, particularly in patients with recurrent/metastatic HNSCC." (PMID 33110476, 2020). "Indeed, the PI3K/Akt/mTOR pathway is over‐activated in various cancers; therefore, the pathway is an attractive therapeutic target because it functions as a convergence point for divergent growth stimuli and regulates cellular processes that are involved in the initiation and maintenance of cancer." (PMID 32463592, 2020). "Notably, hyperactivation of the mTOR/PI3K/AKT pathway is present in virtually all types of tumors as a main consequence of somatic loss of the PTEN phosphatase, which is mutated or epigenetically inactivated in an large number of cancers." (PMID 30972289, 2019). "Moreover, it was shown that it targets the PI3K/AKT/mTOR signalling axis for cancer prevention." (PMID 30609679, 2019). "In support of these findings, a preliminary improved anti-cancer response was observed in a CRC PDX harboring mutated KRAS with intrinsically high AKT activity using GC1118 combined with the dual PI3K/mammalian target of rapamycin (mTOR)/AKT inhibitor BEZ-235, without observed toxicity." (PMID 31771279, 2019). "We suggest that the down-regulated expression of mTOR in the hypoxic conditions found in the tumor microenvironment may lead to declines in the metabolic rate and may be an adaptive mechanism that Spalax uses to resist cancer development." (PMID 30621584, 2019). "However, it has not been elucidated how the level of GOLPH3 expression impacts the activity of the mTOR-signaling pathway, and whether this contributes in different types of cancer cells to the same mechanisms that lead to malignancy." (PMID 30779783, 2019). "Interestingly, a recent report shows that K562 cells express a distinct mTOR-containing complex, mTORC3 (mTOR associated with ETV7) that lacks other mTORC1/2 containing proteins, and is associated with rapamycin-resistance when upregulated in human cancer cells." (PMID 31729420, 2019). "This may, in part, be due to the fact that GOF mutations in the PI3K/mTOR pathway do not appear to be strong drivers of cancer growth." (PMID 31752127, 2019).
cancer (continued). "Therefore, inhibition of the PI3K/Akt/mTOR pathway is critical for cancer therapy." (PMID 31262325, 2019). "In addition to acting as an inhibitor of mTOR, which is hyperactivated in the majority of human cancers, DEPTOR may also act as an oncogene in certain cancers." (PMID 31228948, 2019). "mTOR signaling may promote the survival of cancer cells via enhancing the expression of FANCD2, CHK1 and RRM2 through CDK4/6 while inhibiting ATM, revealing the potential mechanisms of the increased cancer cell growth and proliferation under stressful conditions." (PMID 31285446, 2019). "It has been suggested that inhibiting mTOR signaling could suppress cancer invasion and metastasis." (PMID 31671902, 2019). "The herein research results confirm the hypothesis on the important role of mTOR signaling in cancer progression, and gives hope that implementation of successful combination of its inhibitors will find recognition and application in cancer treatment in the near future." (PMID 30848427, 2019). "However, due to earlier problems, such as unfavorable pharmacokinetic profiles and high in vivo toxicity, there is a continually growing need to discover novel PI3K and/or mTOR inhibitors for further development into therapeutic candidates for cancer treatment." (PMID 30635656, 2019). "To determine whether ALM, a novel compound down-regulates AKT and mTOR activity, can improve anti-cancer efficiency of mTOR inhibitors, we performed experiment to evaluate the effect of ALM in the combination therapy with rapamycin (the classic mTOR inhibitor) or Everolimus." (PMID 31083403, 2019). "Therefore, targeting the mTOR pathway is a promising strategy for cancer prevention and therapy." (PMID 31167465, 2019). "Thus, we posit a mechanism supporting sustained mTOR signaling after genotoxic stress, which may allow enhanced cancer cell survival through radiation resistance." (PMID 31288154, 2019). "Since mTOR signaling regulates fundamental activities including cell cycle, proliferation, growth, and survival, as well as protein synthesis and glucose metabolism, there is no doubt that mTOR has a close association with cancer." (PMID 30754640, 2019). "Therefore, the increased expression of hypoxanthine phosphoribosyl transferase 1 may rescue the defect in purine synthesis due to mTOR inhibition and help cancer cells adapt to mTOR inhibition." (PMID 31277692, 2019). "In this review, we summarize our current knowledge of the structure and functions of Sin1, focusing specifically on its protein interaction network and its roles in the mTOR pathway that could account for various cellular functions of mTOR in growth, metabolism, immunity and cancer." (PMID 34691993, 2019). "Furthermore, the pro- and anti-carcinogenic effects of mTOR and/or AhR activation may be a double-edged sword depending on the type of cancer, the tumor environment and the concurrent anticancer treatment." (PMID 31417567, 2019). "During cancer development, pathways other than mTOR could be activated." (PMID 30592193, 2019). "Moreover, studies have shown that mTOR negatively regulates autophagy in cancer cells." (PMID 30909494, 2019). "In addition, the adsorbed proteins may support mTOR activation and negatively impact on the specificity of NPs to induce apoptosis in cancer cells." (PMID 30642006, 2019). "Since mTOR based regimens lead to Treg expansion which can be considered an undesirable effect in the treatment of cancer, strategies that can selectively deplete Tregs might improve the antitumor effect of mTOR inhibitors by reversing the suppressive effect on the immune system." (PMID 30413837, 2019).
cancer (continued). "Therefore, it will be interesting to determine whether inhibition of CTPS filamentation could suppress mTOR hyperactive cancer cell growth in future studies." (PMID 30857853, 2019). "Our findings suggested that everolimus might not be effective for cancer patients harboring mutations in PI3K/ATK/mTOR pathway and physicians should be cautious about its off‐label use in clinical practice." (PMID 31385461, 2019). "Considering the inhibitory role of C2-ceramide in the AKT pathway and the activation of Csk, C2-ceramide could serve as an effective anti-cancer drug with potential to inhibit the PI3K/AKT/mTOR/p70S6K axis as an Src inhibitor, which is harmful to cell survival." (PMID 30884764, 2019). "Moreover, elevated CASC9 expression in OSCC may play a role in promoting cancer by activating the AKT/mTOR signaling pathway to regulate autophagy." (PMID 30674868, 2019). "Inhibition of the mTOR pathway in the cells may improve the therapeutic index in cancer treatment." (PMID 31075885, 2019). "Upregulation of mTOR signaling can promote tumor growth and progression through diverse mechanisms including the promotion of growth factor receptor signaling, angiogenesis, glyolytic metabolism, lipid metabolism, cancer cell migration, and suppression of autophagy." (PMID 31277692, 2019). "Therefore, inhibition of the PI3K/AKT/mTOR pathway is a therapeutic target for cancer." (PMID 31835352, 2019). "Thus, accumulating evidence indicates that blocking components of the PI3K/mTOR pathway may be a promising approach for HH driven cancers." (PMID 31492956, 2019). "The mammalian or mechanistic target of rapamycin (mTOR) pathway plays a crucial role in regulation of cell survival, metabolism, growth and protein synthesis in response to upstream signals in both normal physiological and pathological conditions, especially in cancer." (PMID 30754640, 2019). "Overall, these findings underscore the role of translation machinery in determining the efficacy of MTOR targeted therapies and suggest that the inability of such approaches to suppress mRNA translation may facilitate metabolic adaptations of cancer cells to KIs." (PMID 30072418, 2019). "Taken together these findings suggest that mTOR inhibitors may act through different mechanisms to induce cell death in a tumor context dependent manner, which makes them suitable for combined therapies to overcome cancer cell resistance." (PMID 31635099, 2019). "Thus, an inhibitor targeting both PI3K and mTOR may have better anti-cancer activity compared to targeting mTOR alone." (PMID 31277692, 2019). "In addition, “mTOR signalling pathway”, “Pathways in cancer”, “Proteoglycans in cancer” and “Signalling pathways regulating pluripotency of stem cells” are present in both tissue and blood DEmiRNAs, which have been shown to be involved in the pathogenesis of glioma." (PMID 31235820, 2019). "Furthermore, the PI3K-Akt-mTOR pathway coordinates the uptake and use of multiple nutrients, such as glucose, glutamine, nucleotides, and lipids, enabling growth and proliferation of cancer cells." (PMID 31159225, 2019). "Therefore, the PI3K/Akt/mTOR signaling is a target for the treatment of cancer." (PMID 30678711, 2019). "However, as the PI3K/Akt/mTOR signalling axis is one of the most commonly activated in human cancers, effective targeting of this pathway will remain of high interest to scientists and clinicians in their hunt for improved cancer therapies for patients." (PMID 35582282, 2019). "Therefore, mTOR must be specifically targeted as an anticancer therapy for the treatment of cancer." (PMID 31030499, 2019). "Hence, a combination of mTOR and Mnk inhibitors is an effective therapeutic strategy for cancer." (PMID 31277692, 2019). "Hence, PI3Kα/mTOR targeting might be a promising strategy for HH-driven cancers that are resistant to SMO inhibitors." (PMID 31492956, 2019).
cancer (continued). "The PTEN/Akt/mTOR signaling pathway plays important roles in the transmission of proliferative signals, and this pathway may be aberrantly regulated in individuals with cancer and contribute to drug resistance and poor prognosis." (PMID 31762813, 2019). "Our results that DRAM1 inhibits PI3K-Akt-mTOR pathway might bridges these two isolated phenomena observed in SCC together and provide a new clue for the potential mechanism underlying the tumorigenesis of this type of human cancer." (PMID 30902093, 2019). "PAH cells share many characteristics with cancer cells, namely a propensity for survival and proliferation under unfavourable, hypoxic conditions, and the involvement of many of the same signalling pathways such as mammalian target of rapamycin (mTOR), HIPPO and growth factor signalling." (PMID 31868216, 2019). "We then review key findings from clinical trials that target mTOR and the lessons we have learned from both pre-clinical and clinical studies that could provide insights on innovative therapeutic strategies, including immunotherapy to target mTOR signaling and the metabolic network in cancer." (PMID 31817676, 2019). "In addition to inducing apoptosis and inhibiting cell division and proliferation by blocking several proliferation-stimulating signaling pathways, it also activates the PDK1/Akt/mTOR survival pathway, which severely compromises ponatinib as an anti-cancer drug." (PMID 30959969, 2019). "Moreover, the correlation between the risk scores from epigenetic signature and ssGSEA scores were analysed and results showed signs of cancer-related hallmarks, e.g. mTOR signalling, G2M checkpoints, MYC targets significantly correlated with the risk scores (FDR q < 0.001)." (PMID 31747912, 2019). "In addition to stimulating autophagic cancer cell death, the induction of autophagy by mTOR inhibitors could also sensitize cancer cells to other cancer therapeutics." (PMID 30266744, 2018). "Thus, assessing PI3K/mTOR expression along with Met expression in cancer samples may provide biomarker value to stratify patients likely to respond to therapies targeting these molecules." (PMID 30406111, 2018). "RPTOR, mechanistic target of rapamycin kinase and MTOR associated protein (mTOR), LST8 homolog (MLST8) constitute the core subunits of the mammalian TORC1 complex which play an important role in controlling cell growth, survival and metabolism and is often deregulated in cancer." (PMID 29933410, 2018). "We further speculate on the consequences of mTOR inhibition in the development of cancer cachexia." (PMID 30061533, 2018). "Although the mechanisms by which merlin suppresses mTOR signaling remain elusive, NF2 inactivation has been found to confer sensitivity to rapalogs in bladder cancer, suggesting that mTORC1 signaling likely sustains the expansion of merlin-deficient cancer cells." (PMID 29565815, 2018). "In addition, mTOR signaling pathways are constitutively activated in many types of human cancer." (PMID 30250638, 2018). "The focus of this part of the review will be mainly on mTOR pathways; however, these pathways are interconnected and they can integrate into an autophagy-related cancer network that could ultimately affect the fate of cancer cells." (PMID 29329237, 2018). "Blocking PD-1 and PD-L1 may reduce glycolysis level in cancer cells by inhibiting mTOR pathway." (PMID 29527212, 2018). "From these findings it is clearly emerging that mTORC1 dysfunctions may be associated not only with prototypical mTOR-opathies such as TSC, but also with some sporadic forms of cancer as well as with different disorders characterized by neuronal development malformations." (PMID 29772672, 2018).